GLT8D1 (glycosyltransferase 8 domain containing 1)
Description:
In vitro, catalyzes the transfer of a galactose residue from UDP-galactose onto GalNAc and GlcNAc structures.
Synonyms: AD-017; FLJ14611; MSTP139
Tractability: Antibody: UniProt predicts a signal peptide or a membrane-spanning region. PROTAC: ubiquitination databases record sites on it; its protein half-life has been measured.
Gene: Protein-coding gene on chromosome 3 (52,694,153 to 52,706,368, reverse strand). Ensembl gene ENSG00000016864.
Subcellular location: Golgi apparatus membrane
Subcellular location (Human Protein Atlas): Golgi apparatus; Centrosome
Gene Ontology:
Molecular function: glycosyltransferase activity; UDP-glycosyltransferase activity
Cellular component: Golgi membrane; membrane
Genetic constraint (gnomAD): Loss-of-function variants: 10 observed, 13.39 expected, observed/expected ratio (o/e) 0.75, 90% interval 0.46 to 1.27. The upper end of that interval is the gene's LOEUF score, 1.27, which puts it in group 5 of 6, group 1 being the genes least tolerant of losing a copy. Missense variants: 193 observed, 212.68 expected, observed/expected ratio (o/e) 0.91, 90% interval 0.81 to 1.02. Synonymous variants: 71 observed, 78.06 expected, observed/expected ratio (o/e) 0.91, 90% interval 0.75 to 1.11.
Gene-disease validity (ClinGen):
ClinGen rates the evidence that GLT8D1 causes each of these diseases.
amyotrophic lateral sclerosis (autosomal dominant): Limited. Amyotrophic lateral sclerosis (ALS) is a neurodegenerative disease characterized by progressive muscular paralysis reflecting degeneration of motor neurons in the primary motor cortex, corticospinal tracts, brainstem and spinal cord.
Homologues: Orthologues: chimpanzee GLT8D1 (99% identical), macaque GLT8D1 (99% identical), pig GLT8D1 (94% identical), dog GLT8D1 (92% identical), guinea pig GLT8D1 (91% identical), mouse Glt8d1 (90% identical), rabbit GLT8D1 (90% identical), rat Glt8d1 (90% identical), tropical clawed frog glt8d1 (63% identical), zebrafish glt8d1 (60% identical). Paralogues in human: GLT8D2 (46% identical).
Diseases named in the same sentence as GLT8D1 in open-access papers:
GLT8D1 is named in the same sentence as 22 diseases in open-access papers, as found by Europe PMC text mining. Sharing a sentence is not in itself a finding about the gene and the disease. The quoted sentences say what the papers report.
schizophrenia (10 papers, 2018 to 2025). A major psychotic disorder characterized by abnormalities in the perception or expression of reality. "Many risk genes shared by schizophrenia and BD have been reported to affect dendritic spine morphogenesis, such as NEK4, GNL3, PBRM1, and GLT8D1." (PMID 37443018, 2023). "Consistently, studies have showed that schizophrenia risk genes (including DISC1, RELN and GLT8D1) have important role in brain development through regulating proliferation and differentiation of neural stem cells." (PMID 30737407, 2019). "Sherlock integrative analysis shows that ALMS1, GLT8D1, and CSNK2B are schizophrenia risk genes, which are validated using independent brain expression quantitative trait loci (eQTL) data and integrative analysis method (SMR)." (PMID 29483533, 2018). "Our eQTL analysis showed that rs2535629 was associated with the expression of GLT8D1, NKE4, and SFMBT1 in the human brain, suggesting that rs2535629 may confer schizophrenia risk by modulating these genes." (PMID 34978167, 2022). "To further test if rs2535629 conferred schizophrenia risk by modulating the expression of NEK4, GLT8D1, and SFMBT1, we examined the expression level of these three genes in brains of schizophrenia cases and controls using data from the PsychENCODE (559 cases and 936 controls)." (PMID 34978167, 2022). "These convergent lines of evidence suggest that the ALMS1, CSNK2B, and GLT8D1 genes may be involved in pathophysiology of schizophrenia." (PMID 29483533, 2018). "Interestingly, differential expression analysis of GLT8D1, SFMBT1, and NEK4 suggested that rs2535629 may confer schizophrenia risk by regulating SFMBT1 expression." (PMID 34978167, 2022). "Fourth, considering that rs2535629 is associated with the expression of GLT8D1, NEK4, and SFMBT1, we could not rule out the possibility that rs2535629 might confer schizophrenia risk by regulating the expression of GLT8D1 and NEK4." (PMID 34978167, 2022). "In addition to GLT8D1 and NEK4, our study also suggests that SFMBT1 may be a potential risk gene at this locus, and functional SNP rs2535629 may confer schizophrenia risk by regulating SFMBT1." (PMID 34978167, 2022). "An additional gene, GLT8D1, proximally located to NEK4, also survived correction the schizophrenia and BIP analyses." (PMID 32398653, 2020). "As we have demonstrated the potential role of GLT8D1 in schizophrenia in our previous study and expression analysis showed no significant change of NEK4 and GLT8D1 in schizophrenia cases compared with controls, we focused on SFMBT1 in this study." (PMID 34978167, 2022).
glioma (6 papers, 2023 to 2025). A benign or malignant brain and spinal cord tumor that arises from glial cells (astrocytes, oligodendrocytes, ependymal cells). "Another study showed that GLT8D1 overexpression is associated with more aggressive disease in human gliomas." (PMID 37277853, 2023). "Two recent studies revealed that GLT8D1 is associated with cell cycle arrest, apoptosis, growth, and self-renewal of glioma stem cells, and promotes migration of human glioblastoma cells." (PMID 37277853, 2023). "Emerging evidence indicates that GLT8D1 functions as an oncogene in head and neck squamous cell carcinoma, glioma and melanoma." (PMID 40963867, 2025). "The upregulation of glycosyltransferase 8 domain-containing 1 (GLT8D1) in cancerous cells, induced by hypoxia or HIF-1α, is associated with more aggressive disease in gliomas." (PMID 39980929, 2025). "GLT8D1 knockdown promotes cell cycle arrest at the G2/M phase and cellular apoptosis in glioma stem cell." (PMID 39980929, 2025). "Previous studies have reported that GLT8D1 is upregulated in multiple malignant tumors, such as head and neck malignancies, melanoma, and glioma, and is significantly correlated with prognosis." (PMID 39628694, 2024). "Glycosyltransferase GLT8D1 and GLT8D2 have been reported to be associated with head and neck squamous cell carcinoma, melanomas, glioma, GBM, and ovarian cancer chemoresistance." (PMID 37277853, 2023). "High-expressed GLT8D1 is confirmed to be correlated with worse clinical outcomes in glioma and glioblastoma." (PMID 37277853, 2023). "Interestingly, the glycosyltransferase 8 domain containing 1 (GLT8D1) was recently shown to contribute to the stabilization of CD133 by interacting with it and influencing its glycosylation in glioma cells." (PMID 38532366, 2024).
melanoma (5 papers, 2021 to 2025). A malignant, usually aggressive tumor composed of atypical, neoplastic melanocytes. "One enzyme of interest, Glycosyltransferase 8 domain containing 1 (GLT8D1), has been associated with the progression of various cancers, such as head and neck squamous cell carcinoma, melanoma, and glioma." (PMID 39628694, 2024). "GLT8D1 overexpression was also recently reported in melanoma to be associated with worse overall survival and progression-free survival." (PMID 33963205, 2021).
amyotrophic lateral sclerosis (3 papers, 2023). "Based on exome sequencing in an autosomal-dominant amyotrophic lateral sclerosis pedigree, mutations in the GLT8D1 gene were associated with the neurodegenerative disease amyotrophic lateral sclerosis." (PMID 38066107, 2023). "Several studies have implied that GLT8D1 dysfunction is linked to neurodegenerative or neurological diseases, such as amyotrophic lateral sclerosis (ALS), frontotemporal dementia (FTD), and schizophrenia." (PMID 37277853, 2023).
gastric cancer (3 papers, 2023 to 2024). A primary or metastatic malignant neoplasm involving the stomach. "However, the association between GLT8D1/2 and gastric cancer (GC) remains unclear." (PMID 37277853, 2023).
head and neck squamous cell carcinoma (3 papers, 2023 to 2025). A squamous cell carcinoma that arises from any of the following anatomic sites: lip and oral cavity, nasal cavity, paranasal sinuses, pharynx, larynx, and salivary glands. "GLT8D1 is reported to play a tumorigenic role in head and neck squamous cell carcinomas and human cutaneous melanomas." (PMID 37277853, 2023). "GLT8D1 overexpression with hypomethylation was reported to act as an oncogene in head and neck squamous cell carcinomas." (PMID 37277853, 2023).
sarcoma (2 papers, 2021 to 2025). A usually aggressive malignant neoplasm of the soft tissue or bone. "Mutations in GLT8D1 have been identified in patients with several sarcomas, suggesting a potential role in tumorigenesis." (PMID 40963867, 2025). "In the 255 sarcomas of the TCGA PanCancer Atlas Studies, alterations were found for SLC25A39,GLT8D1 and GATAD2A in 0.78%, 1.57%, and 2.75% of cases, respectively." (PMID 33963205, 2021).
bipolar disorder (1 paper, 2018). A disorder of the brain that causes unusual shifts in mood, energy, activity levels and the ability to carry out day-to-day tasks. "We noticed that GLT8D1 was also associated with bipolar disorder in a previous GWAS64." (PMID 29483533, 2018).
cutaneous melanoma (1 paper, 2023). A primary melanoma arising from atypical melanocytes in the skin. "GLT8D1 was also confirmed to be upregulated in cutaneous melanomas and might act as a novel prognostic biomarker for an unfavorable prognosis." (PMID 37277853, 2023).
mucosal melanoma (1 paper, 2022). A melanoma that arises from a mucosal site. "The expression of the GLT8D1 protein is higher in both cutaneous and mucosal melanoma than in nevi." (PMID 36143291, 2022). "In addition, GLT8D1 protein expression was higher in cutaneous melanoma compared to mucosal melanoma." (PMID 36143291, 2022).
cancer (6 papers, 2019 to 2024). A tumor composed of atypical neoplastic, often pleomorphic cells that invade other tissues. "Most of these CAF-related genes are associated with tumorigenesis and cancer progression, including GLT8D1, GPX3, NRP1, PPP1R26, SERPINE1, and TMSB15A." (PMID 36717783, 2023). "In view of the several open possibilities, it is necessary to investigate further to find efficient endogenous GLT8D1 substrates, to structurally characterize them and evaluate their role in the mechanisms underlying diseases of the central nervous system and cancer." (PMID 38066107, 2023). "Meanwhile, the causal relationship whether GLT8D1/2 could affect cancer prognosis and response to therapeutic interventions through tumor immunity remains unclear." (PMID 37277853, 2023). "However, few reports have been published regarding the association between GLT8D1 and cancer." (PMID 37277853, 2023). "Although direct evidence linking hypoxia to the stability and functionality of proteins in MDVs is lacking, a recent study links hypoxia and upregulation of HIF-1α to the elevation of GLT8D1 (glycosyltransferase 8 domain containing 1) levels in cancer cells." (PMID 39500350, 2024). "Glycosyltransferase 8 domain-containing protein 1 (GLT8D1) has been associated with central nervous system diseases and cancer." (PMID 38066107, 2023). "Our study found that GLT8D1/2 gene alterations occurred in multiple cancer types, among GC samples, GLT8D1 and GLT8D2 were altered in 3.64% and 1.59%, respectively." (PMID 37277853, 2023). "GLT8D1/2 expression was significantly correlated with multiple signaling pathways or cellular biology involving oncogenesis, cancer development, and clinical prognosis." (PMID 37277853, 2023). "For example, Notch, Hedgehog, FGF, and TGFBR pathways correlated with GLT8D1, while GLT8D2 was significantly linked to PI3K-Akt signaling pathways, pathways in cancer, cell cycle checkpoints, and focal adhesion." (PMID 37277853, 2023). "Our results demonstrated that GLT8D1 was significantly upregulated in the tumor tissues than the corresponding normal tissues in more than half of cancer types (17 out of 33)." (PMID 37277853, 2023). "Additionally, we further investigated the relationship between GLT8D1/2 genes and TMB/MSI, two well-known biomarkers for immune response in cancer." (PMID 37277853, 2023).
tumor (5 papers, 2021 to 2025). "Accordingly, GSEA analysis showed that GLT8D1/2 expression was significantly associated with multiple signaling pathways involving oncogenesis and tumor development." (PMID 37277853, 2023). "Previous research has indicated by bioinformatics analysis that GLT8D1 may serve as a potential prognostic marker for poor prognosis in GC and could be associated with tumor immunity." (PMID 39628694, 2024). "The tumor volume and weight were significantly reduced in the GLT8D1 knockdown group compared with the control group." (PMID 39628694, 2024). "Strikingly, GLT8D1 knockdown also markedly suppressed tumor growth in a xenograft mouse model, underscoring its pivotal role in GC progression." (PMID 39628694, 2024). "Our research demonstrates that GLT8D1 is upregulated in GC tissues, and higher expression levels indicate more advanced tumor stage and poorer prognosis, suggesting that it has the potential to be a novel biomarker for GC progression." (PMID 39628694, 2024). "Next, we constructed the prognostic nomograms with prognosis factors including gender, age, pathologic stage, residual tumor, GLT8D1/2 expression to predict the 1-, 3- and 5-year survival probability." (PMID 37277853, 2023). "Different GLT8D1 expression was observed in groups based on residual tumor, with higher GLT8D1 in R1&R2 than that in R0." (PMID 37277853, 2023). "Univariate regression analysis revealed that several clinical characteristics were related to the OS of GC patients, including age, pathologic stage III&IV, residual tumor, and higher GLT8D1/2 expression." (PMID 37277853, 2023). "Furthermore, IHC provided evidence that the downregulation of GLT8D1 significantly suppresses tumor growth, as indicated by a marked decrease in the expression of the proliferation marker Ki-67 in the tumors with GLT8D1 knockdown." (PMID 39628694, 2024). "Considering the results above, our study suggested that GLT8D1/2 may affect the prognosis of GC patients through tumor immunity, especially GLT8D2." (PMID 37277853, 2023). "The results about GLT8D1 are consistent with previous studies in other tumor types." (PMID 37277853, 2023). "Our findings implied that GLT8D1/2 genes may affect the prognosis of GC patients through tumor immunity, especially GLT8D2." (PMID 37277853, 2023). "GLT8D1/2 may serve as potential prognostic markers of poor prognosis in GC correlated with tumor immunity." (PMID 37277853, 2023). "Neutrophils infiltration, alone or in concert with other immune cells, such as Macrophages, Eosinophils, and Mast cells, also lead to tumor development, which may provide potential mechanism by which GLT8D1/2 affects prognosis." (PMID 37277853, 2023). "Finally, a potential role for SLC25A39 and GATAD2A in tumor development in this patient is weakly supported by literature and the most likely candidate gene appears to be GLT8D1." (PMID 33963205, 2021). "Notably, after screening by multivariate regression analysis, the results showed that clinical parameters including age, pathologic stage IV, residual tumor, and higher GLT8D1/2 expression, were identified as independent prognostic factors for GC patients in this study." (PMID 37277853, 2023). "Third, no fusion transcript shared by all tumors was found and only variations in three genes were detected both in tumor and non-tumor tissues: SLC25A39 (c.C809T),GLT8D1 (c.C955G) and GATAD2A (c.A65G)." (PMID 33963205, 2021). "These variations affected the following genes: AZIN1 (c.A1099G), COG3 (c.A1903G), COPA (c.A490G), GATAD2A (c.A65G), GLT8D1 (c.C955G) and SLC25A39 (c.C809T), and were all verified by Sanger sequencing on tumors and non-tumor DNA." (PMID 33963205, 2021). "The variations in GATAD2A (c.A65G),GLT8D1 (c.C955G) and SLC25A39 (c.C809T) were validated in all sequenced cases both in non-tumor and tumor samples, showing that these variations were constitutive mutations." (PMID 33963205, 2021).
neurodegenerative disease (1 paper, 2020). A disorder of the central nervous system characterized by gradual and progressive loss of neural tissue and neurologic function. "More interestingly, GLT8D1, a GT8 GT with an unknown function implicated in neurodegenerative diseases, is predicted to have a glucosyltransferase specificity." (PMID 32234211, 2020).
GLT8D1 also shares sentences with these, for which no sentence is quoted: glioblastoma (2 papers); psychiatric disorder (2); attention deficit-hyperactivity disorder (1); autism spectrum disorder (1); central nervous system diseases (1); frontotemporal dementia (1); Knee Osteoarthritis (1); major depressive disorder (1); ovarian carcinoma (1).